GPX1 (glutathione peroxidase 1)
Diseases named in the same sentence as GPX1 in open-access papers (continued):
Sharing a sentence is not in itself a finding about the gene and the disease.
cancer (continued). "However, GPX1 may play opposite roles in different types of cancers, and its roles vary in different literature." (PMID 35626163, 2022). "This might be due to the absence of another GPX isoenzyme in monocytes, GPX2, which has been previously shown to have overlapping functions with GPX1 in limiting the redox-dependent activation of the NF-κB pathway and LM biosynthesis in human epithelial-derived cancer cells." (PMID 34681720, 2021). "Hence, therapeutic inhibition of the GPx1 may be a promising approach for potentiating cancer chemotherapy in drug-resistant cells, one which could be pursued by using pentathiepins." (PMID 34299253, 2021). "However, association of altered expression of GPX1 with cancer chemoresistance has never been reported previously." (PMID 31032363, 2019). "Thus, we hypothesized that cancer cells downregulate GPx1 to regulate autophagy in response to glucose deprivation." (PMID 30538220, 2018). "Furthermore, GPX1 level is closely related with cancer risks." (PMID 27404728, 2016). "Recent studies have shown that this gene could be regulated by DNA methylation of regions near the promoter in cancer cells, where a hypermethylation of Gpx1 and the consequent silencing of the gene disturb the redox environment, favouring progression of the disease." (PMID 27010651, 2016). "Among the individuals with the Pro/Pro genotype, the correlation between TBARS concentration and GPx1 activity was positive and significant (r = 0.3043; p = 0.0089) but it was absent in the cancer patients who had one or two polymorphic GPX1 Leu alleles (r = 0.0417; p = 0.7454)." (PMID 26446998, 2015). "Further, Gpx deficiency leads to cancer predisposition and in vivo sensitivity to oxidant-inducing agents is well documented for mice lacking selenocysteine-containing proteins such as Gpx1 and Gpx4." (PMID 26147969, 2015). "Upon H2O2 stimulation, GPX4 expression increased whilst GPX1 decreased, suggesting complementary roles for GPX4 and GPX1 in cancer cells." (PMID 40259435, 2025). "Se nanoparticles also decreased cancer cell viability and proliferation while increasing the mRNA expression of TXN, GPX1, GPX2, GPX3, and GPX4 in many of the cancer cell lines." (PMID 39408290, 2024). "Typically, the high level of oxidative stress in cancer cells (usually caused by tumor microenvironment or drug-induced ROS) would lead to cellular apoptosis rather than survival or transformation due to the inhibition of GPx-1 activity, but not its expression, by the upregulated SELENBP1." (PMID 39728443, 2024). "The role of GPX1 is to utilize GSH for the reduction of H2O2 to water, and it also plays a significant role in the management of cancer therapeutic resistance." (PMID 39061847, 2024). "The lower promoter methylation of GPX1, a member of the GPX family that interact with oxidative stress, results in high expression levels of GPX1 in some cancer cell lines." (PMID 34568341, 2021). "Our results also showed that upon peptide treatment, three proteins reported to sustain high proliferation rates in cancer cells (TRXR1, MMP14 and GPX1) were upregulated in MDA-MB-231 cells." (PMID 33499187, 2021). "In contrast, in cancer cell types with a RIPK3-negative background, the function of GPx1 switched to promoting an antiapoptotic effect." (PMID 34158609, 2021). "As a proof of concept, we targeted loci in healthy donor DNA, including a highly variable hexanucleotide repeat in C9orf72, and four cancer-related genes with guide RNAs previously validated for PCR-free targeted sequencing (GSTP1, KRT19, GPX1, SLC12A4)." (PMID 33830997, 2021). "GPX1 and TRXR1 are intracellular antioxidant enzymes that play a role supporting cancer progression, by counteracting substantial amounts of reactive oxygen species (ROS) generated in tumor cells." (PMID 33499187, 2021). "Glutathione peroxidase-1 (GPX1) is an important member of the GPX family as GPX4, which plays a role in cancer cell proliferation invasion, metastasis, and apoptosis." (PMID 34922551, 2021).
cancer (continued). "From these data, we selected potential biomarkers of cancer including six upregulated proteins (RNF213, CTSG, PGLYRP1, RPL8, S100A8, S100A9) and two downregulated proteins (GPX1, TNS1)." (PMID 34361002, 2021). "Through our analysis, we confirmed higher levels of GPX2 and TXNRD1, and lower levels of GPX1, SELENOF, and SELENOP in the cancer cell lines compared to normal epithelial cells, which has already been observed and reported in the literature." (PMID 32933107, 2020). "To date, studies of selenoproteins raised on the association between Se supplements and cancer prevention, as well as GPX1, GPX2, and GPX3, have been reported with major physiological roles of cancer prevention or development." (PMID 32316597, 2020). "The finding leads us to examine the roles of GPX1, a widely and abundantly expressed member in GPX family, in cancer chemoresistance." (PMID 31032363, 2019). "In this study, we analyzed and explored the public cancer databases (TCGA and ONCOMINE) to conclude that GPX1 is highly expressed in RCC." (PMID 31844035, 2019). "In German patients, GPX1, GPX4, and TXNRD1 were also found to be up-regulated in cancer, compared to the matched tissues for mRNA and/or their corresponding protein levels." (PMID 30469315, 2018). "GPx1 and GPx4, which are key antioxidant enzymes that protect cancer cells from apoptosis and ferroptosis, do not contain canonical AREs and are not considered direct targets of NRF2." (PMID 40818321, 2025). "GPX1 and GPX4 inhibitors have thus shown promise as anti-cancer agents, and targeting other GPX isoforms may prove equally beneficial." (PMID 37244126, 2023). "Gpx1, antioxidant gene also induced by CBD and have role in cancer." (PMID 37796968, 2023). "Despite the fact that earlier studies by other authors have repeatedly shown that inhibition of GPX1, GPX 4, and TXNRD1 contributed to increased oxidative stress in cancer cells, our results indicate an increase in their expression under the influence of the studied agents." (PMID 35743086, 2022). "Since GPx1 depletion greatly enhanced ASK1 activation, we questioned whether GPx1 depletion sufficiently sensitizes cancer cells to apoptosis upon exposure to external stress, such as cytokine storms." (PMID 34158609, 2021). "The ubiquitously expression of GPX1,GPX4,TXNRD1 and TXNRD2 in humans has been reported in previous studies, and our study further confirmed these genes were also ubiquitously expressed in different types of cancer." (PMID 33706760, 2021). "The expression levels of the GPX1 and GPX3 genes were positively correlated with the stromal- and immune-cell scores, and the TXNRD2 gene was negatively correlated with the stromal-cell score for all but a few cancers." (PMID 33706760, 2021). "GPX1 is ubiquitous and its action contributes to diminish DNA damage and inhibit the synthesis of inflammatory mediators whereas GPX2 and GPX3 are overexpressed, mainly, in diverse cancer types." (PMID 33672092, 2021). "Overall, our studies demonstrate that the anti-apoptotic function of GPx1 is dependent on the absence of RIPK3 expression in cancer cells." (PMID 34158609, 2021). "The absence of GPx1 augmented TNF-α-induced apoptosis in various RIPK3-negative cancer cells by markedly elevating the level of cytosolic H2O2, which is derived from mitochondria." (PMID 34158609, 2021). "Thus, GPX1, SELENBP1, SELENON, SELENOK, and SOD2 were differently expressed only in the cancer tissues." (PMID 30469315, 2018). "An unexpected result was the strong staining of GPX1 in the nuclei of both benign prostate tissues and immortalized cells, but not in cancer cells." (PMID 30453672, 2018). "The function of GPx1 is to promote migration, proliferation, and tumor cell invasion, conditioning a potential not yet defined prognostic role, in cancer patients." (PMID 28536671, 2017). "Whether the interaction between GPx-1 and SBP1 impacts their function or has a contributing role in cancer and other diseases remains to be determined." (PMID 26007340, 2015).
cancer (continued). "For example, GPx1 and GPx2 help control the production of pro-inflammatory prostaglandins by regulating COX-2, suggesting that these enzymes may have protective roles in inflammation-related diseases like colitis and cancer." (PMID 39942544, 2025). "Additionally, GPX1, GPX2, and GPX4 expression is upregulated in cancer cells resistant to many chemotherapeutics, and many treatment-resistant cells have been found to accumulate lipid peroxides, showing an increased dependence on the antioxidant activity of GPX4." (PMID 37244126, 2023). "Our data suggest that upregulation of CAT and GPx-1 in senescent cancer cells may be a characteristic feature and may help distinguish them from non-senescent cancer cells." (PMID 36230727, 2022). "The avoidance of H2O2 overproduction is likely to be the cause of no promotion of cancer cells when there is simultaneous overexpression of SOD2 and CAT both in vitro and in vivo and of tumor-preventive and tumor-suppressive effects in the case of the simultaneous overexpression of SOD2 and GPX1." (PMID 36552527, 2022). "Finally, by testing the relationship between the expression levels of these two families of selenoprotein genes in NCI-60 cell lines and drug sensitivity, we found that the TXNRD1, GPX1, GPX2, and GPX3 genes may play a role in the drug sensitivity or drug resistance of cancer cells." (PMID 33706760, 2021). "However, molecular mechanisms regulating GPX1 expression in cancers have never been demonstrated." (PMID 31032363, 2019). "Resveratrol-induced SOD2 expression was observed in cancer cells, although the expression of SOD1, CAT and GPX1 was not affected." (PMID 32316674, 2020). "However, while GPX1 and GPX4 were more highly expressed in tumor tissue from the Czech and Irish cancer groups, respectively, TXNRD1 was not significantly different in any of our tested cohorts." (PMID 30469315, 2018).
tumor (111 papers, 2013 to 2026). "Altered expression of GPX1 has been associated with tumorigenesis by regulating ROS levels that promote tumor survival." (PMID 37795451, 2023). "Immunohistochemical study revealed that the high expression of Gpx-1 was associated with the tumour’s histological grade, proliferating cell nuclear antigen (PCNA) immunohistochemical expression, depth of invasion, and angioinvasion (all p < 0.001)." (PMID 37242524, 2023). "Concerning GPX1 polymorphism, our results indicated that GPX1 genetic variants were significantly associated with the disease stage and tumor grade." (PMID 36676755, 2023). "Another study aimed to explore the role of the glutathione peroxidase-1 (GPX1) gene associated with tumour progression in vitamin D3-mediated progression of salivary adenoid cystic carcinoma (SACC)." (PMID 37299554, 2023). "On the other hand, GPx1 expression has been linked to higher tumor number and growth rate, as well as to chemo/radio resistance." (PMID 32426284, 2020). "Such as, the high expression of GPX1 was significantly associated with nodal metastasis, high grade, depth of tumor invasion, perineural invasion and advanced overall stage, and predicts poor prognosis in oral squamous cell carcinoma." (PMID 31844035, 2019). "C3 also upregulated GPX1, glutathione peroxidase 1, a response protein that facilitates sequestration of cytotoxic oxidants and a described putative tumor suppressor with loss of function in PC-3 cells." (PMID 29464047, 2018). "Since the identification of a well‐characterized functional polymorphism named p.Pro198Leu (rs1050450 C>T) in GPX1 gene, abundant studies have evaluated the association between p.Pro198Leu polymorphism and tumor risk in diverse population." (PMID 29411539, 2018). "A higher frequency of the Leu variant of rs1050450 (GPX1) was found in breast tumour DNA compared to normal tissue, probably due to loss of heterozygosity in the tumour cells." (PMID 24039907, 2013). "The present study aimed to investigate whether dietary Se supplementation affected 4T1 tumoral volume associated with blood Se concentration, hepatic GPx-1 activity and SelP expression, and tumor and metastatic histomorphology." (PMID 36634075, 2023). "Gpx-1 expression was significantly associated with tumour histological grade (p < 0.001, Chi2test)." (PMID 37242524, 2023). "Accordingly, the association of the GPX1 genetic polymorphism with the disease stage and tumor grade which we found in our study indicates that GPX1 could be related to the progression of the disease." (PMID 36676755, 2023). "The substitution of Pro for Leu is thought to lead to a conformational change in the GPX1 protein which may affect tumour susceptibility." (PMID 37446063, 2023). "The expression of GPX1 is directly linked with malignant transformation and tumor spread." (PMID 34943522, 2021). "Indeed, GPx1 inhibits the oxidation of DNA mutations and, therefore, it may inhibit tumorigenesis, and overexpressed GPx1 reduces tumor growth, suggesting its protective effect in tumorigenesis." (PMID 38202704, 2023). "The frequency of the Pro/Leu genotype of the GPx1 gene was higher in patients with BC than in the control group, and additionally, the Pro/Leu genotype was associated with the advanced tumour stage (significantly more common in cases of T2-T4 tumours than T1 tumours)." (PMID 33923108, 2021). "For example, GPx1 has been reported to prevent oxidative DNA mutations, which in turn may prevent the development of tumors, and research shows that overexpression of GPx1 can reduce tumor growth, indicating its inhibitory effect in tumorigenesis." (PMID 32571353, 2020). "GPx1 can also act as an oncogene by regulating proliferation, apoptosis, and migration, among other tumor-promoting effects." (PMID 39796741, 2025). "A crucial antioxidant defense to detoxification of hydrogen peroxide is glutathione peroxidase 1, and genetic variants on GPX1 have been linked with neoplasia development." (PMID 40565143, 2025).
tumor (continued). "GPX1 can also mediate redox homeostasis and tumor progression, which are regulated by glutamate dehydrogenase 1 (GDH1)." (PMID 40346054, 2025). "Genetic variants of antioxidant enzymes, namely in SOD2, GPX1, and CAT, were already associated with the development of various neoplasms and treatment efficacy." (PMID 40565143, 2025). "The level of GPx1/3 is positively regulated with the level of ROS and corresponds to tumorigenicity and tumor stage." (PMID 37968795, 2024). "Pancreatic ductal adenocarcinoma cells can induce protective autophagy via the activation of ROS/AMP-activated protein kinase (AMPK) signaling and GPx1 degradation to survive in a glucose-starved tumor microenvironment." (PMID 39125992, 2024). "Since NF-κB transcriptionally activates GPx1, vitamin D can inhibit the NF-κB pathway and GPX1 expression to reduce tumor malignancy." (PMID 39125992, 2024). "Compared to the untreated EST-tumor group, the GPX1 gene expression was significantly downregulated in Kmp + DXN, and Kmp (p ≤ 0.05)." (PMID 38253759, 2024). "We further verify that expression of three genes identified from our scRNA-seq analyses, thymosin beta 10 (TMSB10), CD74 and GPX1, are expressed at the protein level in hybrid cells within patient-matched primary tumor and peripheral blood." (PMID 38106024, 2023). "The low level of immunohistochemical expression of Gpx-1 protein was found in 30 (88.24%), 33 (48.53%), and 6 (14.63%) of the G1, G2, and G3 tumours, respectively." (PMID 37242524, 2023). "In this study, we analyze the expression of gpx1 to gpx8 genes for the eight known GPx isoforms in brain tissue from healthy control animals and tumor tissue from animals after transplacental ENU administration, also considering gender differences." (PMID 37761814, 2023). "Our work is also the first to show the localisation of Gpx-1 in the tumour tissue at the level of the electron microscope, using the immunogold labelling method." (PMID 37242524, 2023). "It is interesting to note that high levels of Gpx-1 protein expression were found in only 12% of the G1 tumours, 51% of the G2 tumours, and 85% of the G3 tumours." (PMID 37242524, 2023). "By reviewing the literature data, so far only a few studies have been investigating the association of the GPX1 genetic polymorphism with the UBC disease stage and tumor grade and the reported results differ from those obtained in our study." (PMID 36676755, 2023). "In 4 (11.76%), 35 (51.47%), and 35 (85.37%) of the G1, G2, and G3 tumours, respectively, high levels of Gpx-1 protein expression were found." (PMID 37242524, 2023). "After identifying all hybrid cells within a tissue section or peripheral blood slide, we quantified the average fluorescent intensity of each phenotypic marker TMSB10, CD74 and GPX1 across all hybrid and tumor cells from each patient." (PMID 38106024, 2023). "GPX1 is closely related to tumor development, patient survival, and prognosis in a variety of human malignancies." (PMID 35626163, 2022). "Since NF-κB can transcriptionally activate GPX1, vitamin D can inhibit the NF-κB pathway and GPX1 expression to reduce tumor malignancy." (PMID 35626163, 2022). "Previous studies have demonstrated that GPX1 to GPX7 play important roles in the carcinogenesis of tumor." (PMID 35712475, 2022). "Studies have shown that GDH1 promotes tumor growth by activating the reactive oxygen species (ROS)-scavenging enzyme glutathione peroxidase 1 and regulating redox homeostasis through its product a-ketoglutarate (a-KG) and the subsequent metabolite fumarate." (PMID 36249072, 2022). "GPX1 can participate in various signaling pathways to regulate tumor biological behaviors, including cell proliferation, apoptosis, invasion, immune response, and chemoresistance." (PMID 35626163, 2022).